RNU4-69P (RNA, U4 small nuclear 69, pseudogene)
Gene: Small nuclear RNA gene on chromosome 5 (120,710,698 to 120,710,840, reverse strand). Ensembl gene ENSG00000222609.
Homologues: Orthologues: chimpanzee U4 (99% identical), macaque U4 (87% identical), guinea pig U4 (50% identical), mouse Gm56237 (44% identical). Paralogues in human: RNU4-76P (64% identical), RNU4-12P (62% identical), RNU4-67P (62% identical), RNU4-20P (62% identical), RNU4-23P (62% identical), RNU4-68P (62% identical), RNU4-84P (62% identical), RNU4-13P (61% identical), RNU4-42P (61% identical), RNU4-44P (61% identical), RNU4-58P (61% identical), RNU4-70P (61% identical), and 80 more.